BRAF (B-Raf proto-oncogene, serine/threonine kinase)
Diseases named in the same sentence as BRAF in open-access papers (continued):
Sharing a sentence is not in itself a finding about the gene and the disease.
melanoma (continued). "In addition, A375 and A2058 are BRAF mutated melanoma cells." (PMID 32466797, 2020). "Notably, synergistic effects of KRAS/RAF/MEK/ERK inhibitors combined with autophagy inhibitors is not restricted to KRAS-driven PDAC models, but is also observed in NRAS-mutated melanoma, BRAF-mutated colorectal patient derived xenografts (PDXs) models and BRAF-mutant thyroid cancers." (PMID 32878084, 2020). "On the contrary, however, the incidence of the BRAF V600E mutation in benign nevi and premalignant conditions or dysplastic nevi is more frequent (~ 70–88% and ~ 60%, respectively) than in melanoma (~ 40–45%), despite the fact that the conversion rate of benign nevi to melanoma is negligible." (PMID 32066498, 2020). "However, it has to be considered that the BRAF/NRAS mutation frequency is very low in mucosal melanoma, therefore the KIT mutation rate must be much higher in mucosal melanoma as compared to cutaneous locations but a statistical analysis cannot be done on our small cohort." (PMID 31848942, 2020). "In particular, high levels of AXL in melanoma are associated with a transcriptional reprogramming that induces a switch from a proliferative to an invasive phenotype, intrinsically less sensitive to inhibition of the BRAF/MAPK pathway and characterized by low levels of MITF expression." (PMID 33291749, 2020). "Thus, the detection of the BRAF V600E mutation in melanoma samples is used to select patients who should respond to BRAF inhibitors (like vemurafenib or dabrafenib), although unfortunately, most metastatic patients with initial tumor response develop resistance." (PMID 32168325, 2020). "Given that our MPRA assay was conducted in melanoma cells, it may be possible that such variants, for example, may only be functioning in the context of oncogenic signaling (e.g., oncogenic BRAF), tumor suppressor loss (e.g., CDKN2A), or immortalizing events (e.g., mutation of the TERT promoter)." (PMID 32483191, 2020). "Therefore, BRAF or NRAS-mutated melanomas represent the vast majority of patients." (PMID 32664549, 2020). "Hou and colleagues could demonstrate that oncogenic BRAF V6000E in melanoma causes a large number of epigenetic alterations, including decreased expression levels of DNA-methyltransferase 1 (DNMT1) and histone methyltransferase EZH2 affecting CpG island methylation and the epigenetic landscape." (PMID 32046099, 2020). "However, despite several trials and studies having proven the efficacy of immuno checkpoint inhibitors and targeted therapies in OS, no direct comparison has been performed so far, and the choice between the two therapeutic approaches in BRAF mutated melanoma is still debated." (PMID 32695793, 2020). "Consequently, we stated that Snail1 could be essential during a metastatic cascade of melanomas with BRAF mutation." (PMID 32046241, 2020). "Therefore, we aimed at analyzing the heterogeneity in the mutational load of BRAF V600E in biopsies of melanoma patients of different stages at diagnosis, in order to investigate if the mutational load of BRAF V600E could serve as a useful prognosis factor." (PMID 32168325, 2020). "Furthermore, splice variants in V600E BRAF-mutant-positive malignant melanoma patients were shown to be associated with vemurafenib resistance, indicating that aberrant splicing could be a novel mechanism of acquired resistance." (PMID 33334367, 2020). "Interestingly, inhibition of PARP reduces motility and invasion of BRAF-mutated melanoma cells." (PMID 33133138, 2020). "However, the BRAF (V600E) mutation, the predominant oncogene associated with melanoma, may explain the transition from benign neoplasm to malignancy." (PMID 32430073, 2020). "As a considerable proportion of ATC samples have been shown to co-harbor BRAF and PI3K pathway alterations, it will be further relevant to determine whether these PI3K pathway alterations confer intrinsic resistance to BRAF inhibition, as observed in BRAF-mutated melanoma." (PMID 31277524, 2019).
melanoma (continued). "In addition, preclinical MEK inhibitor activity has been shown in BRAF-mutated melanoma." (PMID 30956763, 2019). "Furthermore, the study carried out in tumor microenvironment induced drug resistance showed that various BRAF mutated melanoma and ERBB2+ breast cancer cell lines when co-cultured with different fibroblasts affected the sensitivity to vemurafenib and lapatinib, respectively, via HGF/c-MET pathway." (PMID 30680600, 2019). "Finally, mucosal melanomas mutated on BRAF and NRAS may also be sensitive to MEK inhibitors as well as MEK inhibitor-based combinations." (PMID 31398831, 2019). "We have investigated the impact of signaling by RAC1, an oncogene which is mutationally activated in 4% of melanomas and may be activated by alterations in upstream regulators in a larger fraction, showing that RAC1P29S promotes the initiation of melanoma driven by mutant BRAF or NF1 loss." (PMID 31257073, 2019). "The observation of a responding molecularly defined BRAF-mutated pilocytic astrocytoma is intriguing in light of the recently discovered ability of vorinostat to induce apoptosis by increasing reactive oxygen species (ROS) levels in BRAFV600E-mutated melanomas." (PMID 31823832, 2019). "Keeping in mind that many melanoma patients carry a BRAF mutation, and that they develop resistance to BRAF inhibitors, this observation is very interesting as MIF inhibitors could be used to treat many patients in relapse after a treatment with a mutant BRAF inhibitor." (PMID 31013837, 2019). "In addition to select patients with melanomas for targeted therapy, mutational status, such as BRAF vs. NRAS mutation or p.V600E vs. p.V600K BRAF mutations may affect clinicopathological characteristics and outcomes." (PMID 31277584, 2019). "In addition to diagnostics and clinical-pathological classification into superficial spreading, nodular, lentigo maligna, and acrolentiginous melanomas, recent molecular diagnostics can delineate subtypes of melanoma (possessing mutations in BRAF, NF1, RAS, or triple wild type)." (PMID 30357519, 2019). "Additionally, aberrant activation of RAS signaling during BRAF V600E mutation maintains an active chromatin state at the mutate hTERT promoters of human melanoma, which facilitates the recruit of RNA polymerase II thereby leading to transcriptional activation of hTERT." (PMID 31404068, 2019). "However, it is quite controversial whether the BRAF mutational status has a prognostic effect in advanced melanoma." (PMID 30626368, 2019). "Although BRAF mutations are commonly identified in many solid tumors and the response of BRAF p.V600E-positive tumors to targeted therapy is well documented, BRAF rearrangements are less frequent and are predominantly found in low-grade glioma, melanoma, lung, colorectal, and thyroid carcinoma." (PMID 31010895, 2019). "Consistent with this, comparison between the top and bottom 75 TCGA melanomas ranked by the Elvidge hypoxia signature using gene set variation analysis (GSVA) revealed a strong down‐regulation of a mitobiogenesis signature previously associated with BRAF inhibitor resistance." (PMID 31207090, 2019). "However, it is imperative to ascertain the detection rate and kinetics of other common melanoma‐associated mutations to determine whether they can be effectively used for patient surveillance, particularly in BRAF WT cases." (PMID 30312528, 2019).
melanoma (continued). "Interestingly our data confirm in all BRAF mutated melanoma cell lines analysed that FOXD3 mRNA is upregulated, however it never precedes temporally upregulation of NRG1, which, to our opinion, remains therefore the principal driver of adaptive resistance to BRAF and MEK inhibitors." (PMID 31557826, 2019). "Moreover, several malignancies such as melanoma, thyroid carcinoma, and although at lower frequency, colorectal cancer and non-small cell adenocarcinoma of the lung carcinoma may harbor the BRAF V600E mutation." (PMID 31762942, 2019). "Recently, exome sequencing in melanoma with high heterogeneity has identified a large catalogue of recurrent somatic variants, which were found to be mostly within the B-Raf proto-oncogene, serine/threonine kinase (BRAF) and Neuroblastoma RAS viral oncogene homolog (NRAS) genes." (PMID 30544544, 2018). "The involvement of BRAF in podocyte survival in vitro is interesting and needs to be further understood considering that treatment with BRAF inhibitor, dabrafenib, associated with the development of nephrotic syndrome in melanoma patients and podocyte injury in vitro." (PMID 30083135, 2018). "It was also noted that BRAF-mutant CRC had lower MPAS compared to that of melanoma and thyroid cancer, which may provide some underlying mechanisms for the poorer outcomes observed in BRAF-mutant CRC patients treated with BRAF or MEK1/2 inhibitor as single agent or in combination." (PMID 29872725, 2018). "A series of 32 melanoma cell lines - eight derived from surgically-excised primary melanomas, seventeen from cutaneous or lymph nodal metastases - were firstly investigated for mutations in the three main genes (BRAF, NRAS, and CDKN2A) involved in melanoma pathogenesis." (PMID 29492214, 2018). "As hyperactivation of the MAPK pathway has previously been demonstrated to enhance resistance to MAPK pathway inhibitors, we speculated that loss of USP28 in BRAF (V600E) melanoma cell lines would limit sensitivity of these cells lines to the BRAF inhibitor vemurafenib." (PMID 29880484, 2018). "Similarly, it recently has been shown that unsupervised clustering of transcriptional profiles including the top 3000 most variant genes of melanoma patient derived cell lines that developed resistance after long term exposure to BRAF or BRAF/MEK inhibitors, distinguished two different clusters." (PMID 29192388, 2018). "Indeed selective RAF inhibitors have demonstrated clear survival benefit in oncogenic BRAF (predominantly the BRAFV600 mutation)-driven melanomas (approximately 50% of patients;) and results in near-complete abrogation of MAPK signaling in tumors harboring such mutations." (PMID 29423085, 2018). "Indeed, melanoma is a heterogenic tumor, and some studies including ours have suggested that MIC could be responsible for the metastatic potential of melanoma, which could be implicated in resistance to BRAF inhibitor therapies." (PMID 30186236, 2018). "Additionally, BRAF V600 K mutations also occur frequently in BRAF-mutated melanoma (7–19%)." (PMID 29739364, 2018). "In another study, ACY-1215 could also accelerate the death of melanoma cells with a BRAF mutation caused by vemurafenib through inducing ER stress and inhibiting ERK activation, which provides a preclinical basis for the treatment of vemurafenib resistant malignant melanoma patients." (PMID 30176876, 2018). "From these results, we proposed the following hypothesis of the genetic evolution of melanoma: melanoma is generated by a large number of genetic mutations, including those in BRAF (clusters 1 and 2), and only those cells with certain mutations are selected under selective pressure." (PMID 30701024, 2018). "A further difference between BRAF-mutated melanoma and colorectal cancer is that BRAF-mutated colorectal cancer cells possess higher levels of PI3K activation than BRAF-mutated melanoma cells, and that resistance to vemurafenib could be overcome by combining vemurafenib with PI3K inhibitors." (PMID 29312543, 2017).
melanoma (continued). "The same metabolic pathways that have been targets for investigation in other malignancies have also been explored in BRAF-mutated melanoma, but a consensus of the major metabolic program exhibited by BRAF-mutated melanomas, or even whether a single dominant metabolic program exists, is lacking." (PMID 28205616, 2017). "However, the use of “off-label” GDT should not be the norm since the activity of a drug targeting a particular mutation is different for distinct tumor types (e.g. BRAF inhibitors are very efficacious in BRAFV600E mutated melanoma, but lack the same activity in BRAFV600E mutated colon cancer)." (PMID 28854908, 2017). "However, BRAF V600 mutations, the most frequent and therapeutically best-targetable gene alteration in cutaneous melanoma (present in ~50% of cases) is only rarely found in mucosal melanomas (≤ 10% of cases), which limits clinical treatment options." (PMID 28380455, 2017). "Interestingly, miR-193a-3p was reported as downregulated in BRAF mutation with respect to wild-type melanoma suggesting that miR-193a-3p may have a role in BRAF-associated events." (PMID 29038785, 2017). "Therefore, these drugs may constitute a new effective strategy for the treatment of BRAF-mutated human melanomas, capable of overcoming the resistance to vemurafenib." (PMID 28107182, 2017). "Given the observed heterogeneity in PLX4720 responses without an obvious biological mutational trend and the variable metabolic strategies employed by our panel of BRAF-mutated melanomas, we sought to examine more closely whether a direct relationship exists between metabolism and drug response." (PMID 28205616, 2017). "However, it highlights certain treatment options that may be helpful such as BRAF inhibitors in BRAF mutated melanoma and SRS alone or combined with systemic treatment for suitable patients." (PMID 28819707, 2017). "Furthermore, NF1-associated drug resistance to RAF and EGFR inhibitors, tamoxifen and retinoic acid, has been observed in melanoma, lung cancers, breast cancers and neuroblastoma, respectively, and melanoma cells with BRAF/NF1 mutations develop resistance to BRAF inhibitors." (PMID 28637487, 2017). "Moreover, PARK2 gene is frequently mutated in melanoma cell lines or tumors harboring either BRAF or RAS mutation 75, which may contribute to the accuracy of genetic diagnosis of melanoma patient." (PMID 28544818, 2017). "It was thus possible to conclude that mutated BRAF exerts multiple regulatory effects on melanomagenesis through the induction or the repression of a complex network of miRNAs whose targets are responsible for the promotion or the suppression respectively of melanoma growth." (PMID 28118616, 2017). "Moreover, a study in BRAF-mutant melanoma suggested that PTEN (p.T321fs) mutation may affect PTEN function with PTEN (p.T321fs) mutation-inducing resistance to BRAF inhibitors." (PMID 29100343, 2017). "We analyzed 100 FFPE samples from primary melanoma with three different techniques to determine the mutational status of BRAF and test which could be the most sensitive method to identify mutations in the BRAF V600 codon." (PMID 28039443, 2017). "The case of BRAF mutations is even more intriguing because activating oncogenic BRAF mutations are found in several other tumors, including colorectal, thyroid, lung cancer but in the majority of those cases they are not predictive of drug response to the same BRAF inhibitors as in melanoma." (PMID 28903768, 2017). "Thus small molecule PDK inhibitors such as AZD7545, might be promising drugs for combination treatment in melanoma patients with activating RAS/RAF/MEK/ERK pathway mutations (50% BRAF, 25% NRASmut, 11.9% NF1mut)." (PMID 28595656, 2017). "Importantly, NF1 mutations have been found in melanomas that lack both BRAF and NRAS mutations, with 25–30% of such melanomas found to harbour deleterious NF1 mutations, thus implying that NF1 inactivation has conferred aberrant MAPK pathway activation in these tumours." (PMID 28637487, 2017).
melanoma (continued). "Lacking of miR-195 expression in melanoma patients seems to be one of the main mechanisms of PHB1 accumulation in melanomas which could decrease the efficacy of chemotherapy and even target therapies like vemurafenib used in melanoma patients harboring BRAF V600E mutation." (PMID 29126391, 2017). "Thus, 32 melanomas were assessed regarding their BRAF V600E mutational status." (PMID 28662062, 2017). "Additionally, despite of the successes of BRAF inhibitors in therapy of melanoma patients with BRAF mutation, there are only half of these patients demonstrated effective in the process of treatment and almost all patients will be eventually resistant to inhibitors." (PMID 29371951, 2017). "However, patients with BRAF-mutated melanoma may result insensitive ab initio or, mostly, develop acquired resistance to the treatment with this molecule." (PMID 29113311, 2017). "Curtin and colleagues postulate that since N-RAS activates both the PI3K and MAPK pathway, while BRAF only activates the latter, it may suggest that in melanoma pathogenesis, somatic mutations activating one pathway require another event to activate other pathways." (PMID 27941674, 2016). "Therefore, we examined the effect of dssPLA2 on BRAF V600E mutation gene to melanoma therapy." (PMID 26884744, 2016). "Indeed, primary resistance to targeted therapies might occur despite of the presence of a targetable alteration: response rates reach a ceiling at 65% in BRAF-mutated melanoma treated by BRAF inhibitors, and 71% in EGFR-mutated lung cancer." (PMID 27340923, 2016). "Until recently, therapeutic options for melanoma (outside of early excision for thin melanomas which have a good prognosis) have had little to offer in terms of survival but recent targeted therapies with BRAF inhibitor drugs for tumors with BRAF mutations have improved survival." (PMID 27158185, 2016). "However, key questions to be answered are whether BRAF-mutated melanomas, with intrinsic resistance to BRAF and/or MEK inhibitors, also have primary cross-resistance to PI3K/mTOR inhibitors and which is the frequency of such cross-resistant phenotype." (PMID 26678033, 2016). "Data from cell lines and patients indicate that a subset of mutated BRAF melanomas with high levels of ZEB1 expression may be intrinsically insensitive to BRAFi and MEKi, suggesting that melanoma patients with high levels of ZEB1 expression may not benefit from MAPKi treatment." (PMID 27596438, 2016). "One melanoma was wild-type for BRAF and NRAS (M214) with an unknown driver mutation." (PMID 27545456, 2016). "However, hyper-activation of the MAPK-pathway is found in over 90% of melanomas with approximately 50% of all patients displaying mutations in the kinase BRAF, and approximately 28% of all patients harboring mutations in the MAPK-pathway up-stream regulator NRAS." (PMID 27200346, 2016). "In addition to mutations, loss of RASA1 expression was frequently observed in metastatic melanoma samples on melanoma tissue microarray (TMA) and a low level of RASA1 mRNA expression was associated with decreased overall survival in melanoma patients with BRAF mutations." (PMID 26993606, 2016). "Our work shows that mutated BRAF melanoma patients with high levels of ZEB1 expression may not benefit from MAPKi treatment and that ZEB1 could serve as a predictive marker in order to stratify BRAF‐mutated melanoma into MAPKi‐sensitive and MAPKi‐resistant subgroups." (PMID 27596438, 2016). "However, BRAF mutation status has been hypothesized to predict disease recurrence and response to chemotherapy in melanoma patients." (PMID 26143635, 2015). "Furthermore, as EZH2 mutations in melanoma are coincident with BRAF mutations they may serve to complement the function of BRAF (i.e. BRAF signaling drives cell division, whereas EZH2 signaling drives motility/migration)." (PMID 25671303, 2015).